PCCA (propionyl-CoA carboxylase subunit alpha)
Description:
This is one of the 2 subunits of the biotin-dependent propionyl-CoA carboxylase (PCC), a mitochondrial enzyme involved in the catabolism of odd chain fatty acids, branched-chain amino acids isoleucine, threonine, methionine, and valine and other metabolites. Propionyl-CoA carboxylase catalyzes the carboxylation of propionyl-CoA/propanoyl-CoA to D-methylmalonyl-CoA/(S)-methylmalonyl-CoA. Within the holoenzyme, the alpha subunit catalyzes the ATP-dependent carboxylation of the biotin carried by the biotin carboxyl carrier (BCC) domain, while the beta subunit then transfers the carboxyl group from carboxylated biotin to propionyl-CoA (By similarity). Propionyl-CoA carboxylase also significantly acts on butyryl-CoA/butanoyl-CoA, which is converted to ethylmalonyl-CoA/(2S)- ethylmalonyl-CoA at a much lower rate. Other alternative minor substrates include (2E)-butenoyl-CoA/crotonoyl-CoA (By similarity).
Tractability: Small molecule: a structure with a bound ligand is known. PROTAC: ubiquitination databases record sites on it; its protein half-life has been measured.
Target class: Enzyme; Ligase
Gene: Protein-coding gene on chromosome 13 (100,089,015 to 100,530,437, forward strand). Ensembl gene ENSG00000175198.
Subcellular location: Mitochondrion matrix
Subcellular location (Human Protein Atlas): Mitochondria
Pathways (Reactome):
Metabolism: Biotin transport and metabolism; Propionyl-CoA catabolism
Disease: Defective HLCS causes multiple carboxylase deficiency
Gene Ontology:
Molecular function: enzyme binding; propionyl-CoA carboxylase activity; protein binding; biotin binding; ATP binding; ligase activity, forming carbon-carbon bonds; metal ion binding
Biological process: succinyl-CoA biosynthetic process; branched-chain amino acid metabolic process; fatty acid metabolic process; short-chain fatty acid catabolic process
Cellular component: catalytic complex; mitochondrial matrix; mitochondrion; cytosol
Genetic constraint (gnomAD): Loss-of-function variants: 19 observed, 28.28 expected, observed/expected ratio (o/e) 0.67, 90% interval 0.47 to 0.99. The upper end of that interval is the gene's LOEUF score, 0.99, which puts it in group 4 of 6, group 1 being the genes least tolerant of losing a copy. Missense variants: 419 observed, 425.38 expected, observed/expected ratio (o/e) 0.99, 90% interval 0.91 to 1.07. Synonymous variants: 155 observed, 153.84 expected, observed/expected ratio (o/e) 1.01, 90% interval 0.88 to 1.15.
Gene-disease validity (ClinGen):
ClinGen rates the evidence that PCCA causes each of these diseases.
propionic acidemia (autosomal recessive): Definitive. An organic aciduria caused by the deficient activity of the propionyl Coenzyme A carboxylase and is characterized by life threatening episodes of metabolic decompensation, neurological dysfunction and that may be complicated by cardiomyopathy.
Homologues: Orthologues: chimpanzee PCCA (99% identical), macaque PCCA (97% identical), dog PCCA (91% identical), guinea pig PCCA (90% identical), mouse Pcca (89% identical), rat Pcca (89% identical), pig PCCA (87% identical), rabbit PCCA (86% identical), tropical clawed frog pcca (76% identical), zebrafish pcca (74% identical), Caenorhabditis elegans pcca-1 (56% identical). Paralogues in human: PC (38% identical), MCCC1 (38% identical), ACACB (31% identical), ACACA (29% identical).
Diseases named in the same sentence as PCCA in open-access papers:
PCCA is named in the same sentence as 18 diseases in open-access papers, as found by Europe PMC text mining. Sharing a sentence is not in itself a finding about the gene and the disease. The quoted sentences say what the papers report.
propionic acidemia (13 papers, 2018 to 2025). "Propionic acidemia (PA) is a rare autosomal recessive metabolic disorder caused by mutations in the PCCA and PCCB genes, which encode subunits of the mitochondrial enzyme propionyl-CoA carboxylase (PCC)." (PMID 40044943, 2025). "Propionic acidemia (PA) is a metabolic disorder caused by a deficiency of the mitochondrial enzyme propionyl‐CoA carboxylase (PCC) due to mutations in the PCCA or PCCB genes, which encode the two PCC subunits." (PMID 40302352, 2025). "Propionic acidemia (PA) is a rare metabolic disorder caused by mutations in the propionyl-CoA carboxylase (PCC) gene (PCCA or PCCB), leading to reduced PCC activity and impaired propionyl-CoA metabolism." (PMID 40177291, 2025). "Propionic acidemia is a severe inherited metabolic disorder, caused by the deficiency of propionyl-CoA carboxylase which encoded by the PCCA and PCCB genes." (PMID 35331292, 2022). "Propionic acidemia (PA) (OMIM#606054) is a rare autosomal recessive disorder of metabolism caused by mutations in the PCCA or PCCB gene, which leads to deficiencies of the propionyl CoA carboxylase (PCC) enzymes." (PMID 35296328, 2022). "Propionic acidemia (PA) is a rare autosomal recessive disorder of metabolism caused by mutations in the PCCA or PCCB gene, leading to propionyl CoA carboxylase (PCC) enzyme deficiencies." (PMID 35296328, 2022). "Propionic acidemia (PA), one of the most frequent life-threatening organic acidemias, is caused by mutations in either the PCCA or PCCB genes encoding both subunits of the mitochondrial propionyl-CoA carboxylase (PCC) enzyme." (PMID 33503868, 2021). "PCCA codes for the alpha subunit of the mitochondrial enzyme Propionyl-CoA carboxylase, and mutations in this gene leads to enzyme deficiency and are associated with propionic acidemia." (PMID 36539902, 2022). "Propionic acidemia (PA; MIM#606054) is a rare autosomal recessive metabolic disorder caused by mutations in the PCCA and PCCB genes." (PMID 40044943, 2025). "Propionic acidemia (PA) is an ultrarare disorder caused by deficiency of the mitochondrial enzyme, propionyl-CoA carboxylase (PCC), composed of PCCA and PCCB subunits." (PMID 36577040, 2023). "Propionic acidemia (PA) is a severe monogenic disorder characterized by a deficiency of the mitochondrial protein propionyl-CoA carboxylase (PCC) enzyme, which is caused by mutations in the PCCA or PCCB gene." (PMID 33183246, 2020). "Propionic acidemia (PA)(OMIM#606054) is an inborn error of branched-chain amino acid metabolism, caused by defects in the propionyl-CoA carboxylase (PCC) enzyme which encoded by the PCCA and PCCB genes." (PMID 32819290, 2020).
long QT syndrome (2 papers, 2021 to 2023). "In addition, it was reported that mutations in the PCCA gene were related to long QT syndrome, which is often associated with FA." (PMID 37894937, 2023). "The PCCA gene encodes the mitochondrial propionyl-CoA carboxylase, and mutations in this gene lead to an enzyme deficiency resulting in propionic acidemia, often associated with long QT syndrome." (PMID 34827661, 2021).
Chorea (1 paper, 2022). Chorea (Greek for 'dance') refers to widespread arrhythmic involuntary movements of a forcible, jerky and restless fashion. "For example, ‘childhood onset dystonia or chorea’ (PanelApp panel 847) is most frequently due to propionic acidemia, which in turn is caused exclusively by mutations in the PCCA and PCCB genes." (PMID 35456490, 2022).
epilepsy (1 paper, 2022). A brain disorder characterized by episodes of abnormally increased neuronal discharge resulting in transient episodes of sensory or motor neurological dysfunction, or psychic dysfunction. "A number of prioritized signals of putative pathogenicity were observed that have no reports of association with epilepsy in the literature including SEC24D, PCCA, MYO5A which may be strong candidates for further functional studies." (PMID 36539902, 2022).
gastric cancer (1 paper, 2019). A primary or metastatic malignant neoplasm involving the stomach. "Frameshift mutations resulting in premature termination of translation of Propionyl-CoA Carboxylase Alpha Subunit (PCCA) have been reported in colon and gastric cancer." (PMID 31337362, 2019).
Insulin resistance (1 paper, 2024). Increased resistance towards insulin, that is, diminished effectiveness of insulin in reducing blood glucose levels. "Previous studies showed a downregulation of BCAA degradation pathway genes, including PCCA/B and MMUT, in insulin resistance/T2DM, while a GWAS noted an association between insulin resistance and a region downstream of MMUT." (PMID 38271099, 2024).
Obesity (1 paper, 2017). Accumulation of substantial excess body fat. "Other hub genes, including CCDC50, ORMDL3, PCCA and NAALAD2, have diverse cellular functions and have not been previously implicated as obesity candidate genes." (PMID 28496128, 2017).
metabolic disorder (8 papers, 2020 to 2025). "PA is a rare metabolic disorder caused by mutations in PCCA or PCCB genes, resulting in impaired propionyl-CoA metabolism." (PMID 39975893, 2025). "However, in the rare disease known as propionic academia (PA)—a recessive metabolic disorder caused by mutations in the Propionyl-CoA Carboxylase Subunit Alpha (PCCA or PCCB genes)—impaired metabolism of propionyl-CoA leads to a variety of metabolic disorders." (PMID 40801563, 2025).
cancer (3 papers, 2019 to 2025). A tumor composed of atypical neoplastic, often pleomorphic cells that invade other tissues. "Furthermore, analysis of plasma membrane fractions revealed that mitochondrial matrix proteins were also detected on the cancer cell surface, further supporting our observations of the noncanonical translocation of mitochondrial matrix protein PCCA." (PMID 41132421, 2025).
tumor (3 papers, 2019 to 2025). "PCCA, an enzyme involved in the catabolism of odd-chain fatty acids and multiple-branched amino acids, has been implicated in tumor progression." (PMID 39744168, 2025). "PCCA knockdown slowed tumor growth and reduced lung metastasis, whereas PCCA overexpression promoted tumor growth and lung metastasis." (PMID 39744168, 2025). "Conversely, blocking MMA production in A375 cells by knockdown of PCCA, a component of propionyl-CoA-carboxylase, repressed their ability to induce the activation and infiltration of fibroblasts in the tumor in vivo." (PMID 36266345, 2022). "Moreover, PCCA knockdown suppressed CRC tumor growth and lung metastasis, accompanied by an increase in M1-macrophage polarization." (PMID 39744168, 2025). "Some adhesion molecules play an important role in tumor recurrence, metastasis, and invasion.(Okegawa, Pong, Li, & Hsieh, 2004) Based on the construction of PPI network and module analysis, ACAA1, ACADSB, ALDH6A1, AUH, HADH,and PCCA with high degree of connectivity were selected as hub genes." (PMID 30793530, 2019).
PCCA also shares sentences with these, for which no sentence is quoted: breast carcinoma (1 paper); cardiomyopathy (1); colon cancer (1); glioma (1); Hyperammonemia (1); organic acidemias (1); prostate adenocarcinoma (1); Ventricular arrhythmia (1).